IL10 (interleukin 10)
Diseases named in the same sentence as IL10 in open-access papers (continued):
Sharing a sentence is not in itself a finding about the gene and the disease.
Granuloma (continued). "We compared the cytokine response (Th1, Th17, IL-10) and proliferation (Ki67) of CD4+ and CD8+ T cells to Mtb-specific antigens in lymph nodes without granulomas, with <50% granuloma involvement, and with >50% involvement." (PMID 32790739, 2020). "The granuloma index was not affected by TNF-α blockade in the active disease group, but significantly reduced the levels of IFN-γ, IL-12p40, IL-17 and IL-10 in all antigenic stimulus conditions tested." (PMID 29543912, 2018). "For direct comparison, we simulated the same 1,337 granulomas three additional times in the absence of IL-10, TGF-β1, or both IL-10 and TGF-β1 to create virtual IL-10 knockout (KO), TGF-β1 KO, and double KO sets, respectively." (PMID 29326718, 2017). "In spite of microscopic morphological similarities, significant differences were seen between late stage granulomas of the lung compared to those of the tracheobronchial lymph nodes for IL-17A, IFN-γ, TGF-β, IL10 and IL-22 but not for TNF-α." (PMID 27902779, 2016). "Additionally, significant differences were noted between granulomas from two different thoracic lymph nodes that both receive afferent lymphatics from the lungs (i.e., tracheobronchial and caudal mediastinal lymph nodes) for TNF-α, IL-17A, IFN-γ, TGF-β and IL-10 but not for IL-22." (PMID 27902779, 2016).
type 1 diabetes (98 papers, 2006 to 2026). "In this disease, there is an association between the circulating interleukin-10 (IL-10) levels and the degree of albuminuria in patients with DN in the development of type 1 diabetes (DM)." (PMID 35054831, 2022). "Specific cell subsets that are associated with regulation, and B cells actively producing IL-10 after ex vivo stimulation, have been evaluated to ascertain if Breg frequencies are altered in type 1 diabetes." (PMID 34616408, 2021). "Our data also highlight the role of key Treg molecules, CTLA-4, CD25, IL-10 and IL-2, genetically associated with the development of type 1 diabetes, in the response to infection." (PMID 28815218, 2017). "However, IL-10 was found to increase the risk of nasal polyps, and type 1 diabetes, indicative of eosinophilic asthma." (PMID 39026678, 2024). "In the present study, through a detailed phenotypic analysis, we show that HIPs are not better than conventional islet epitopes in eliciting IFN-γ, IL-10, or IL-17 specific T cell responses in both patients with type 1 diabetes and high-risk unaffected family members." (PMID 34262563, 2021). "With regard to bone biology, loss of IL-10 exacerbated early Type-1 diabetes-induced bone loss." (PMID 31795299, 2019). "Therefore, we aimed to analyze the levels of cytokines, IL-6, TNF-α, VEGF, and IL-10, in serum of girls with type 1 diabetes and find out whether estrogen receptor α polymorphism has relevance for their production." (PMID 24523574, 2014). "The frequencies of total Bregs in the peripheral blood mononuclear cells (PBMCs), including Tim-1+ Bregs, IL-35+ Bregs, and IL-10+ Bregs were found decreased in patients with type 1 diabetes (T1D) compared with those in the HC." (PMID 40458534, 2025). "In another study, HSV vectors were used to express IL-10 in a Type I diabetes rat model by reducing the expression of Toll-like receptor 4 (TLR4), which reduced macrophage activation and inhibited painful neuropathy." (PMID 39598601, 2024). "It was previously demonstrated that obese and overweight children with type 1 diabetes have low serum levels of IL-10, an interleukin that inhibits inflammatory responses in parallel with high levels of IL-17, a pro-inflammatory cytokine." (PMID 37180128, 2023). "The percentage of CD3+CD4+ T lymphocytes with the intracellular expression of IFN-γ+, IL-2, IL-4, IL-10 and IL-17 in the patients with type 1 diabetes and in the control group was analyzed." (PMID 36768715, 2023). "In NOD mice, overexpression of IL-10 can dramatically induce Treg cells and therefore ameliorates the development of type 1 diabetes." (PMID 34394099, 2021). "In a 2009 Phase I study in individuals with type 1 diabetes, those who were given low doses of proinsulin peptide showed an increase in peptide-specific IL-10 responses when compared with individuals given placebo, demonstrating proof of concept." (PMID 28770318, 2017). "Lactobacillus kefiranofaciens M and lactobacillus kefiri K were reported to mitigate progression of type 1 diabetes through inhibiting pro-inflammatory and inflammatory cytokines and elevating the production of IL-10." (PMID 28538869, 2017). "Both of these devices represent model systems that will be used, in future studies, to further evaluate IL-10 induction by HA, with the objective of improving the survival and function of transplanted islets in the setting of autoimmune (type 1) diabetes." (PMID 23971054, 2013). "In patients with type 1 diabetes, peripheral blood mononuclear cells of patients with DR Exhibit higher levels of IL-10, suggesting that IL-10 may play an important role in the regulation of inflammation in DR." (PMID 40687727, 2025). "In addition, IL‐10 secretion by unstimulated peripheral blood mononuclear cells was significantly increased in patients with NPDR developing from type 1 diabetes." (PMID 40464192, 2025).
type 1 diabetes (continued). "However, as these relations are diminished when IL-10/IL-17 ratios are analyzed, we can presume that proper immune balance is most crucial in the process of the insulin-dependent diabetes control." (PMID 36091019, 2022). "A therapy that includes an oral vaccine for type 1 diabetes (T1D) using live attenuated Salmonella MvP728 (ΔhtrA/ΔpurD), cytokines (IL10 and TGFβ) and preproinsulin (PPI) antigen in combination with a sub-therapeutic dose of anti-CD3 mAb was developed by our team." (PMID 34108968, 2021). "To fill those knowledge gaps, we generated BDC2.5+ NOD mice with Il-10 deficiency (BDC2.5+Il-10-/- NOD mice) and investigated the action of IL-10 in modulating diabetogenic CD4+ T cells, neutrophils and the gut microbiota in type 1 diabetes development." (PMID 34394099, 2021). "In an experiment in which anti-CD20 antibodies depleted B cells in NOD mice, MDSC amplified, inhibited the function of CD4+ and CD8+T cells through cell-to-cell contact and released IL-10 and NO, ultimately inhibiting the development of type 1 diabetes in mice." (PMID 34975496, 2021). "The reports of the role of IL-10 in the development of type 1 diabetes are conflicting." (PMID 34394099, 2021). "Impaired functions of IL-10+ B cells in type 1 diabetes (T1D) patients have been confirmed." (PMID 33936028, 2021). "Furthermore, in terms of epitope hierarchy, the native epitope, C13-32, elicits the most frequent IFN-γ and IL-10 responses in patients with type 1 diabetes and preclinical subjects respectively consistent with our previous studies." (PMID 34262563, 2021). "Additionally, we assessed the concentrations of IFN-γ, IL-2, IL-4 and IL-10 in the plasma of individuals with type 1 diabetes and healthy group." (PMID 34830017, 2021). "However, the generation of IL-10+ B cells from both individuals with type 1 diabetes and those with multiple islet autoantibodies was significantly impaired compared to healthy donors." (PMID 34616408, 2021). "Taken together, Breg cells seem to play a protective role in the development of type 1 diabetes in an IL-10-dependent manner, suggesting that Breg cells may be a potential target for the treatment of type 1 diabetes." (PMID 34108975, 2021). "However, in another study, the risk alleles for type-1 diabetes such as PTPN22, interleukin (IL)-27, and IL-10 loci were shown to protect against CD." (PMID 30862129, 2019). "Similar to the original data, this subset captured increasing IL-10/TGF-β bias and decreasing IL-1/NFκB bias across the continuum created by the siblings with low HLA risk, individuals with type 1 diabetes, siblings with high HLA risk and unrelated control individuals." (PMID 30167736, 2018). "In the non-obese diabetic (NOD) mouse model of Type 1 diabetes, disease progression is associated with gradual loss of pancreatic IL-10-secreting FoxP3+ Tregs." (PMID 23755052, 2013). "Cumulatively, these findings suggest that IL-10 and IL-5 may play an important role in modulating the course of Type 1 diabetes in tolerized individuals." (PMID 20949090, 2010). "Therefore, Il-10 deficiency in BDC2.5+ NOD mice significantly affects the activation, proliferation, and function of CD4+ T cells, and thus contributes to the development of type 1 diabetes." (PMID 34394099, 2021). "A selective targeting of this phenomenon, by either correcting the aberrant production of TI-IFN or by preventing its modulation of IL-10 signaling, could significantly improve the efficacy of some approaches currently being explored for the treatment of type 1 diabetes." (PMID 30061883, 2018). "Studies in patients with relapsing-remitting multiple sclerosis or type 1 diabetes demonstrated that ex vivo-activated B-cells produced less IL-10 than B-cells from healthy subjects, suggesting that insufficient IL-10 secretion by B-cells might facilitate autoimmune pathogenesis in humans." (PMID 27045291, 2016).
type 1 diabetes (continued). "IL-10 downregulates CXCR3 expression on CD4+ Th1 cells, and expression of this cytokine has been shown to be elevated in individuals with type 1 diabetes, specifically those who are older at onset." (PMID 41273416, 2026). "Elevated inflammatory cytokines, including TNF-α, IL-6, IFN-α, IL-1β, IFN-γ, IL-10, IL-12, and MIP-1β, have been observed after consumption of a high-fat meal in both individuals with type 1 diabetes (T1D) and healthy individuals." (PMID 40216734, 2025). "Genome-based approaches for identifying genetic polymorphisms associated with Type 1 diabetes (such as IL-2RA and CUX2) have revealed specific SNPs (such as PTPN22, IL-10, IL-27, and IL18RAP) with contrasting effects on the development of Type 1 diabetes." (PMID 38474087, 2024). "Conversely, the SNP rs3024505 within IL-10 and the rs4788084 locus near IL-27 and NURP1 genes exhibit protective roles against the onset of Type 1 diabetes." (PMID 38474087, 2024). "In the treated type 1 diabetes mouse model, serum TNF-α, IL-12, and IFN-γ secretion were greatly reduced in the OI group, whereas CXCL1 and IL-10 production was restored." (PMID 36918798, 2023). "In subjects with type 1 diabetes, C-peptide-NPY elicits the highest interferon-γ response, C-peptide-IAPP2 the highest IL-10 and IL-17 responses were observed at a similar magnitude for C-peptide-IAPP1, C13-32, and C22-A5." (PMID 34262563, 2021). "Taken together, by depleting Il-10 in BDC2.5+ NOD mice, we generated a markedly accelerated model of type 1 diabetes." (PMID 34394099, 2021). "Taken together, our data suggested that altered gut bacteria from BDC2.5+Il-10-/- NOD mice modulated neutrophil homeostasis, which play a role in the development of type 1 diabetes." (PMID 34394099, 2021). "Our study provides novel insights into the role of IL-10 in the modulation of neutrophils and CD4+ T cells in BDC2.5+ NOD mice, and suggests important crosstalk between gut microbiota and neutrophils in type 1 diabetes development." (PMID 34394099, 2021). "In vitro treatment with 1,25(OH)2D3 reduced proinflammatory cytokines (IL-6, CCL-2, IL-23A, IL-15) whereas anti-inflammatory cytokines (IL-10 and PD-L1) rose both in APS-type 1 diabetes and APS-Addison ́s disease." (PMID 33365026, 2020). "In the present study, we observed that STZ-type 1 diabetes in rats induced a significant increase of plasmatic levels of IL-2 and IFN-γ (Th1 cytokines) and a decrease of IL-4 (Th2 cytokine) and IL-10 (regulatory cytokine) concentrations." (PMID 29317893, 2017). "These included IL-6 signaling, IL-10 signaling, TREM1 signaling, MIF regulation of innate immunity, type I diabetes mellitus signaling, p38 MAPK signaling, toll-like receptor signaling, and acute phase response signaling." (PMID 21777429, 2011). "In addition, we showed that in the group of patients with type 1 diabetes with anti-EBNA-1 antibodies in the IgG class, the percentage of CD3+CD4+IL-10+ T cells was significantly higher (p = 0.033)." (PMID 36768715, 2023). "Besides, one study reported that higher PA levels (> 250 min/week) were related to a better inflammatory profile (up-regulation of IL-10 and down-regulation of TNF-α) in children with type I diabetes." (PMID 35813370, 2022). "To date, type 1 diabetes studies reporting differences in IL-10+ B cells have not evaluated IL-10 secretion." (PMID 34616408, 2021). "Recently, in children with type 1 diabetes, a decrease in both the CD24hiCD27+ (B10) and transitional CD24hiCD38hi IL-10+ B cells but not in CD38hiCD27+IL-10+ plasmablasts was found." (PMID 34616408, 2021). "As example, SIGN1R (expressed by APCs and the analogous of the human dendritic cell-specific ICAM-grabbing non-integrin - DC-SIGN) signaling was shown to result in the expansion of IL-10-secreting Treg cells, preventing the development of autoimmune diseases such as EAE and type 1 diabetes (T1D)." (PMID 30538706, 2018).
type 1 diabetes (continued). "Fas ligand drives insulitis in the non-obese diabetic mouse model of type 1 diabetes (T1D) and negatively regulates IL-10-producing (IL-10pos) CD5+ B cells in pancreata." (PMID 28439273, 2017). "Protection from type 1 diabetes requires B cell IL-10 productionsince the adoptive transfer-activated NOD-IL-10--/-- B cells do not confer protectionfrom type 1 diabetes or the severe insulitis in NOD recipients." (PMID 23566714, 2013). "First, we review recent findings that blockade of IL-10/IL-10R interaction can resolve chronic viral infection and second, we reflect on how neutralization of the chemokine CXCL10 can abrogate virus-induced type 1 diabetes." (PMID 17162375, 2006). "In studies of type 1 diabetes mellitus (T1DM) mouse models, exogenous supplementation of C-peptide was found to aid in the reduction of pro-inflammatory cytokines such as IL17 and tumor necrosis factor-alpha (TNFα), and anti-inflammatory cytokines, like IL4 and IL10, in the urine (P <0.05)." (PMID 37745697, 2023). "In animal studies it has been shown that extracts of soluble S. mansoni worm or eggs antigens induced secretion of anti-inflammatory cytokines including IL-10, IL-4 and IL-5 from T cells and subsequently prevented development of type 1 diabetes in non-obese mice." (PMID 35077485, 2022). "However, there have been no studies yet that linked inflammatory biomarkers CRP, IL-6, IL-10, TNF-α, and NF-κB in saliva from adult individuals with type 1 diabetes with and without microvascular complications." (PMID 35788667, 2022). "However, currently there are no reports of alterations in these IL-10 independent regulatory B cell populations, either in number or function, in human type 1 diabetes; thus their contribution to type 1 diabetes remains an outstanding question." (PMID 34616408, 2021). "So far in type 1 diabetes, the studies employing CD40L and TLR stimulants - either LPS [TLR4] or CpG [TLR9] in culture before assessment, or with PMA/ionomycin alone - have shown a decrease in numerical frequency of IL-10-producing B cells from peripheral blood samples." (PMID 34616408, 2021). "This group found that coculture significantly increased the TGF-β, IL-10, IL-6, and PGE2 cytokine levels and skewed toward Foxp3+ regulatory T cells, suggesting a switch to anti-inflammatory T helper 2 (Th2) signaling in a type 1 diabetes model treated with hBM-MSC-EVs." (PMID 30923617, 2019). "Additionally, the most significant canonical pathways were IL-6 signaling, IL-10 signaling, TREM1 signaling, MIF regulation of innate immunity, type I diabetes mellitus signaling, p38 MAPK signaling, toll-like receptor signaling, and acute phase response signaling." (PMID 21777429, 2011). "Tregs can modify immune responses by suppressing effector T cell responses or secreting the cytokines IL-10 and TGF-β to create immunological tolerance, even though IL-10 may be the most promising of the anti-inflammatory interleukins being researched to prevent type 1 diabetes." (PMID 40299229, 2025). "The levels of anti-inflammatory (IL-35, IL-10, IL-4) and proinflammatory (TNF-α, IL-12, IL-18) cytokines were statistically comparable between the type 1 diabetes patients with Hashimoto’s disease and those without." (PMID 39273664, 2024).